CCL3 (C-C motif chemokine ligand 3)
Diseases named in the same sentence as CCL3 in open-access papers (continued):
Sharing a sentence is not in itself a finding about the gene and the disease.
glioblastoma (7 papers, 2015 to 2025). The most malignant astrocytic tumor (WHO grade IV). "Pre-conditioning the vaccine site with a potent recall antigen (e.g., tetanus/diphtheria toxoid) significantly enhances DC migration bilaterally and improves the survival of glioblastoma patients, and this phenomenon is dependent on the chemokine CCL3 in murine models." (PMID 37705736, 2023). "Recent transcriptomic analyses of pHGG-associated microglia have further underscored their role in tumor growth, with these cells expressing substantially less pro-inflammatory cytokines like CCL3/456 compared to microglia in adult glioblastoma (GBM)." (PMID 41497590, 2025). "Genes that show higher expression in astrocytoma compared to glioblastoma were CX3CL1, CSF1 (MCSF), CCL3 (MIP1α), CCL4 (MIP1β), TGFα, FLT3LG, CXCL5, CCL19 while KITLG (SCF) and NGF were equally expressed in the two tumor types." (PMID 35301393, 2022). "Vice versa, transfection of the human glioblastoma cell line U-373 MG with a C/EBPD expression vector led to a significant upregulation of C3, CXCL9, CP, CCL3, TNFAIP6, and IL-6 mRNA levels." (PMID 26230261, 2015).
Hepatitis (7 papers, 2016 to 2025). Inflammation of the liver. "Deletion of the CCL3 gene in mice resulted in a decrease in the M1/M2 ratio and showed improvement in hepatitis when the mice were on a high-fat diet." (PMID 40077628, 2025). "Although CCL3 and CCL5 are hepatitis associated, precisely how their expression is regulated remains unclear." (PMID 27994596, 2016). "Immature neutrophils circulating in advanced MASH patients also expressed an array of pro-inflammatory chemokines that can aggravate and perpetuate liver inflammation, such as CCL2, CCL3, CCL5, CXCL1, and XCL2." (PMID 38791066, 2024). "In Ad-HBV-infected mice, CCL3 and CCL5 contributed to the recruitment of effector immune cells to the liver and promoted hepatitis." (PMID 27994596, 2016).
leishmaniasis (7 papers, 2012 to 2024). Infectious disease that is transmitted through the bite of hematophagous female phlebotomine sand flies. "The role of CC-chemokines CCL2, CCL3 and CCL5 in leishmaniasis has been tested in a number of studies." (PMID 22679519, 2012). "Additional chemokines, including the monocyte chemoattractant protein-1 (MCP-1/CCL2) and macrophage inflammatory protein 1a (MIP-1a/CCL3), have been proposed as potential immunotherapeutic agents for leishmaniasis, although current studies have only focused on their use in the treatment of VL." (PMID 39460345, 2024). "The observed strain differences and the double peak of CCL3 and CCL5 in CcS-16 females provide a novel potential starting point for investigation of the impact of inter-individual differences in chemokine response on pathogenesis of leishmaniasis." (PMID 22679519, 2012). "We took advantage of the published human dataset and a murine model of increased pathology induced by the colonization of S. epidermidis to evaluate whether there is an association between the Staphylococcal species colonization and the expression of CCL3 and CCL4 in the leishmaniasis lesions." (PMID 38709823, 2024). "Besides, the chemokine MIP-1α (CCL3) is known to induce IL-1, IL-6, and TNF-α production with chemotactic and pro-inflammatory effects and acts as homeostasis promoter culminating in a Th1 response in the presence of receptors CCL3 and CCR5, fundamental in the control of leishmaniasis." (PMID 34253188, 2021).
pancreatic cancer (7 papers, 2013 to 2025). "CCL3 has also been reported for MO/MΦ chemoattaction in hepatocarcinoma and pancreatic carcinoma." (PMID 26155942, 2015). "However, the role of the CCR5 ligands CCL3, CCL5 and CCL8 in pancreatic cancer remains controversial." (PMID 35954489, 2022).
synovitis (7 papers, 2016 to 2025). Inflammation of a synovial membrane. "Whereas CCL2 and CCL3 returned to baseline levels within 24 h, CCL5 and CCL11 remained elevated from baseline for 72 h in the synovitis model." (PMID 33980227, 2021). "Furthermore, to confirm that CCL3/MIP1α and S100A8 were specific markers of SM, we also immunostained serial sections of synovial tissue from patients with moderate synovitis using the positive control macrophage marker CD68." (PMID 27044395, 2016).
acute coronary syndrome (6 papers, 2012 to 2025). Signs and symptoms related to acute ischemia of the myocardium secondary to coronary artery disease. "In one previous study in patients with acute coronary syndromes, CCL3 was associated with an increased risk of fatal events during follow-up." (PMID 35211520, 2022). "CCL3 has been reported to act as a biomarker for fatal events in patients with acute coronary syndrome, thus suggesting a specific role in ischemic injury." (PMID 37234258, 2023). "The aim of this study was to investigate the prognostic importance of chemokines CCL3/MIP-1α, CCL5/RANTES and CCL18/PARC for the risk of future cardiovascular events in patients with acute coronary syndromes (ACS)." (PMID 23029252, 2012). "Notably, chemokines CCL3, CCL5 and CCL18 were identified as the risk factors of short-term mortality in patients with acute coronary syndromes." (PMID 36231033, 2022). "Hazard Ratios (95% confidence intervals) for a fatal future cardiovascular event during follow-up in patients with the acute coronary syndrome, according to baseline levels of CCL3/MIP-1α, CCL5/RANTES and CCL18/PARC, Bad Nauheim ACS II registry." (PMID 23029252, 2012). "CCL3, also known as macrophage inflammatory protein-1 alpha (MIP-1α), is a chemokine that plays a critical role in recruiting and activating immune cells during inflammatory responses and it is recognized as a contributing factor to poor prognosis in acute coronary syndrome (ACS)." (PMID 40242450, 2025).
AIDS (6 papers, 2012 to 2020). A syndrome resulting from the acquired deficiency of cellular immunity caused by the human immunodeficiency virus (HIV). "Increased NK cell activity reflected by higher cytotoxic capacity, IFN-γ and chemokines (CCL3, CCL4, and CCL5) production, has been associated with resistance to HIV infection and delayed AIDS progression, demonstrating the importance of these cells in the antiviral response." (PMID 30386329, 2018).
Autoimmunity (6 papers, 2018 to 2023). The occurrence of an immune reaction against the organism's own cells or tissues. "The upregulated transcript levels for IL-23A and CCL3 were found associated with high incidence of autoimmunity." (PMID 31781116, 2019). "MC-secreted cytokines and chemokines encoded by IL1B, TNF, CCL3, and CCL4, all of which contribute to autoimmunity and inflammation, may stimulate other cell populations expressing their homologous receptors." (PMID 36301664, 2022). "They should also assess whether CCL3 facilitates better control over bystander or self-reactive B cell clones in GCs and conveys better protection against development of autoimmunity." (PMID 30271404, 2018). "A role for CCL3, CCL4, CCL5 and their receptor CCR5 in Treg mediated suppression has been previously reported in autoimmunity and cancer and we demonstrate through blockade experiments both these pathways to be of fundamental importance in cells from IGRA-ve controls." (PMID 30231065, 2018).
bladder cancer (6 papers, 2023 to 2025). "CCL3 has been shown to be produced by myeloid cells in bladder cancer patients, which contribute to the pathogenesis of inflammation and immunosuppression." (PMID 36672328, 2023). "For example, in an animal model of bladder cancer, treatment with EZH2 inhibitor enhanced the infiltration of NK cells into the tumor microenvironment, through upregulation of CCL3." (PMID 40551137, 2025). "By means of a 34‐cytokine and chemokine immunoassay panel, we revealed that chemokines including CCL3, CCL4, CCL5, CXCL9, and CXCL10, are robust negative correlated with expression of BCAT2 in human and murine bladder cancer cell." (PMID 36642843, 2023).
bronchiolitis (6 papers, 2010 to 2025). Inflammation of the bronchioles characterized by swelling of the bronchioles and mucus accumulation. "CCL3 mRNA and protein are both detected in bronchoalveolar lavage (BAL) samples of infants infected with RSV, and CCL3 protein levels correlate with the severity of hypoxia in bronchiolitis." (PMID 20195359, 2010). "Nasal aspirates obtained from infants hospitalized with severe RSV-induced bronchiolitis contained higher levels of CCL3, neutrophils, monocytes and Th2-CD8+ T cell subtypes, suggesting that these markers in the nasal tissue correlate with the severity of pathology in the LRT." (PMID 37795093, 2023).
Cerebral ischemia (6 papers, 2011 to 2025). Restriction of arterial blood supply to the brain associated with insufficient oxygenation to support the metabolic requirements of the tissue. "Following cerebral ischemia, a cascade of inflammatory mediators including cytokines (TNF, IL-1α, IL-1β, IL-6, IL-10, TGFβ1) and chemokines (MCP-1 [CCL2], Mip-1α [CCL3], RANTES [CCL5]) is initiated." (PMID 22028848, 2011).
dementia (6 papers, 2006 to 2024). Loss of intellectual abilities interfering with an individual's social and occupational functions. "Exceptions were the association for Beta-NGF and all-cause dementia as well as the associations of CCL3, CCL20, and IL20-RA with vascular dementia, which became statistically significant with the best fitting function." (PMID 36085081, 2022). "In contract, patients with dementia were more likely to have low to midrange CCL3 levels." (PMID 35865985, 2022). "However, the association between dementia and CSF CCL3 levels were nonlinear." (PMID 35865985, 2022). "The results show that CSF chemokine concentration of MCP-1/CCL2, MIP-1α/CCL3, MIP-1β/CCL4, RANTES/CCL5, IL-8/CXCL8 and fractalkine/CX3CL1 is positively correlated with the severity of dementia and the viral load, indicating HIV induced brain damage." (PMID 16712719, 2006). "CSF samples with undetectable CCL3, CCL4 or CCL5 levels were almost entirely from nondemented patients, and detectable CSF CCL3 and CCL4 were both associated with dementia." (PMID 35865985, 2022). "Our study highlights the changes and potential contributions of several chemokines (CXCL1, CCL3, CXCL5, CXCL6, CCL3, CCL19), interleukins (IL8, IL6-RA, IL18-BP), and other immune markers (OSM, ALCAM, OPG, CHIT1, YKL-40, STAMBP, MMP-9, MMP-10) in the prodromal and dementia phases of AD." (PMID 31694701, 2019).
encephalitis (6 papers, 2013 to 2025). An acute inflammatory process affecting the brain parenchyma. "IL-2, CXCL10, CCL3, IL-10, CCL22, and IL-6 may represent new biomarkers in patients with anti-NMDAR encephalitis." (PMID 33408682, 2020). "Expression of CCL3, CCL5, CCL7 and CCL19 chemokines could play a crucial role in recruitment of IFN-γ-producing CD8+ T cells into the brain, and in facilitating migration of effector macrophages for prevention of Toxoplasma encephalitis during acute stage of encephalitis." (PMID 23374751, 2013).
esophageal squamous cell carcinoma (6 papers, 2020 to 2025). Esophageal squamous cell carcinoma (ESCC) is a type of esophageal carcinoma (EC) that can affect any part of the esophagus, but is usually located in the upper or middle third. "show that CCL3 derived from both tumor-associated macrophages and esophageal squamous cell carcinoma (ESCC) cells promotes cell migration and invasion of ESCC cells via binding CCR5." (PMID 32457351, 2020). "CCL3 derived from esophageal squamous cell carcinoma (ESCC) cells and TAMs binds to CCR5, activating Akt and ERK pathways to promote ESCC cell invasion and migration." (PMID 39941858, 2025). "It has also been reported that in esophageal squamous cell carcinoma, TAMs express and secrete CCL3, which contributes to tumor migration, invasion, and angiogenesis by binding CCR5 and activating the PI3K/Akt pathway." (PMID 33971970, 2021). "In esophageal squamous cell carcinoma (ESCC), gram-negative bacterial enrichment drives LPS accumulation, which activates the CCL3/CCL5–CCR1–MAPK axis to upregulate tumor PD-L1 while suppressing T cell proliferation/cytotoxicity, elevating PD-1/LAG-3, and reducing CD107a/IFN-γ." (PMID 41181090, 2025).
HCMV infection (6 papers, 2010 to 2023). "In murine cytomegalovirus infection and in Toxoplasma gondii infection, early release of CCL3 and CCL4 from APCs is vital for the influx of NK cells into affected tissues, and these cells are an important source of IFN-γ, which induces macrophages and dendritic cells to secrete CXCL9 and CXCL10." (PMID 20828409, 2010). "In particular, HCMV infection led mainly to the over-expression of CCL2, CCL3, CCL11, CXCR4, IL-1β, IL13, MMP1, MMP3, MMP9 and MMP13, SERPINA1, TNFα, and BMP7, and the gradual and constant downregulation of IL13RA2 (up to almost 800-fold at 14 days p.i.)." (PMID 32899126, 2020).
migraine (6 papers, 2018 to 2025). "Elevated levels of CCL3 have been reported in patients with migraine, which could support the hypothesis that VM shares migraine mechanisms." (PMID 31214186, 2019). "The levels of CCL18, CCL3, and CXCL4 were different between patients with MD or migraine and controls." (PMID 34575163, 2021). "Levels of IL-1β, CCL3, CCL4, CXCL1, CCL22, and CCL8 were also measured in 55 healthy controls and 64 migraine patients." (PMID 34575163, 2021). "A study of migraine patients revealed that CCL3 and CXCL8 were both found to be increased interictally in blood serum from patients with migraine in contrast to healthy control individuals." (PMID 35295531, 2021). "Additionally, differential expression of CCL3 and CCL5 has been reported to be able to be used to distinguish between patients with migraine and those with tension-type headache." (PMID 35295531, 2021). "Therefore, a comparison between VM patients and migraine patients, namely IL- 1β, CCL3, CCL22, and CXCL1 levels, could be beneficial to understand if there is a shared cytokine profile between migraine and VM or if this cytokine signature is specific to VM." (PMID 31214186, 2019). "Therefore, we measured the levels of IL-1β, CCL3, CCL4, CXCL1, CCL22, and CCL18 in a cohort of 83 patients with MD, which included 44 EOMD and 39 LOMD, and 64 patients with migraine without vestibular symptoms to control the effect of migraine itself on cytokine levels." (PMID 34575163, 2021).
myocarditis (6 papers, 2012 to 2025). Myocarditis is a condition that is characterized by inflammation of the heart muscle (myocardium). "CCL3 is proposed as a requirement for virus-induced inflammatory response, as CCL3-deficient mice were resistant to Coxsackievirus-induced myocarditis." (PMID 32194558, 2020). "The beneficial effect of Met-RANTES on ECG abnormalities and decrease in TNF and CCL3 concentrations in heart paralleled the reduction of myocarditis intensity, mainly due to decrease in the numbers of CD8+ and F4/80+ cells invading the heart tissue." (PMID 32194558, 2020). "CCL3-defficient mice were resistant to Coxsackie virus-induced acute myocarditis seen in infected wild-type mice." (PMID 32194558, 2020). "Therefore, CCL3 became a molecule of interest to be explored in the pathophysiology of the T. cruzi-elicited CD8-enriched myocarditis." (PMID 32194558, 2020). "This peptide inhibits the inflammatory chemokines CCL2, CCL3, CCL7, and CCL8 in murine Coxsackievirus B3 (CVB3) infection, a viral trigger of myocarditis." (PMID 40009121, 2025). "To explore the participation of CCL3 in CCC, we assessed the intensity and cell composition of the T. cruzi-elicited myocarditis." (PMID 32194558, 2020). "More importantly, our findings place CCL3 as a key chemokine in chronic T. cruzi infection, as a putative sponsor for the CD8+ T-cells and macrophage-enriched myocarditis, in a scenario with abundant IFNγ, TNF and CCL3." (PMID 32194558, 2020). "A putative role for CC-chemokines in CCC physiopathology was raised by the demonstration that the concentrations of CCL3 and CCL5 in the cardiac tissue paralleled the intensity of myocarditis in acute and chronically Colombian-infected C3H/He mice." (PMID 32194558, 2020). "Mice lacking CCL3 have a reduced inflammatory response to influenza virus and are resistant to coxsackievirus-induced myocarditis." (PMID 23144764, 2012). "The intensity of acute and chronic T. cruzi-elicited myocarditis is related to the concentrations of the CC-chemokines CCL3/MIP-1α and CCL5/RANTES, but not to the concentrations of IFNγ and TNF in the cardiac tissue." (PMID 22532799, 2012).
neuropathic pain (6 papers, 2015 to 2025). Chronic pain caused by damage to nerve fibers. "Our results reveal for the first time that cenicriviroc lowers the CCL3 level and simultaneously enhances opioid analgesia, suggesting its importance in opioid efficacy during neuropathic pain; however, further in-depth research is needed for confirmation." (PMID 33408720, 2020). "EE can relieve neuropathic pain by reducing inflammatory mediators, such as proinflammatory cytokines (IL-1β, TNF-α, IL-6) and chemokines (CCL2, CCL3), among others, increasing anti-inflammatory substances (IL-10, Arg-1, CX3CL1) in the periphery and CNS." (PMID 40190342, 2025). "Thus, Ccl3 antagonists may be potential new drugs for the treatment of neuropathic pain." (PMID 29164149, 2017).
peritonitis (6 papers, 2016 to 2025). Inflammation of the peritoneum (tissue that lines the abdominal wall and covers most of the organs in the abdomen). "Animals with peritonitis had higher levels of inflammatory proteins such as CCL3, IL17A and IL6 in abdominal fluid and serum compared to sham." (PMID 40102905, 2025). "Early production of CCL3, as well as CCL2 and cytokines such as IL-1β, IL-6, IL-12, and IL-1Ra, was observed in an acute antigen-induced peritonitis model, showing that peritoneal-resident cells are an important source of these mediators." (PMID 30937315, 2019). "Moreover, we would suggest that Nrf2 activation in zymosan-induced peritonitis could limit neutrophil activation and auto-recruitment mainly via the regulation of TNFα, CXCL2 and CCL3 production in the peritoneal fluid." (PMID 31419224, 2019).
retinal degeneration (6 papers, 2016 to 2023). Degeneration of the retina. "Several lines of evidence suggest that Ccl3, Ccl4, and Il6 are important mediators of pathogenic activity by macrophages in retinal degeneration, which may account for the neuroprotective action of NR58-3.14.3." (PMID 26911327, 2016). "In a mouse model of retinal degeneration, microglia expressing CCL3 were shown to exacerbate inflammation and retinal degeneration, which were attenuated in CCL3 knock-out mice." (PMID 31616310, 2019). "Several cytokines and chemokines including MIP-1α (CCL3), MIP-1β (CCL4), MCP-1 (CCL2), MCP-3 (CCL7), TNF-α, IL-1β and IL-6 have been implicated in photoreceptor-microglial crosstalk and retinal degeneration." (PMID 27814376, 2016). "Novel peaks were also seen at the Ccl3 and Ccl4 chemokine genes, as well as the interferon activated gene Ifi204 and the Cd68 surface marker —both of which were shown to become acutely accessible in a light damage model of retinal degeneration." (PMID 37880237, 2023).